LRSAM1 (leucine rich repeat and sterile alpha motif containing 1)
Description:
E3 ubiquitin-protein ligase that mediates monoubiquitination of TSG101 at multiple sites, leading to inactivate the ability of TSG101 to sort endocytic (EGF receptors) and exocytic (HIV-1 viral proteins) cargos. Bacterial recognition protein that defends the cytoplasm from invasive pathogens. Localizes to several intracellular bacterial pathogens and generates the bacteria-associated ubiquitin signal leading to autophagy-mediated intracellular bacteria degradation (xenophagy).
Synonyms: TAL; FLJ31641; CMT2P; RIFLE
Tractability: PROTAC: UniProt records ubiquitination sites on it; ubiquitination databases record sites on it; its protein half-life has been measured.
Gene: Protein-coding gene on chromosome 9 (127,451,469 to 127,503,503, forward strand). Ensembl gene ENSG00000148356.
Subcellular location: Cytoplasm
Subcellular location (Human Protein Atlas): Cytosol
Pathways (Reactome):
Immune System: Antigen processing: Ubiquitination & Proteasome degradation
Gene Ontology:
Molecular function: protein binding; ubiquitin protein ligase activity; ubiquitin-protein transferase activity
Biological process: negative regulation of endocytosis; positive regulation of autophagosome assembly; positive regulation of xenophagy; protein autoubiquitination; protein catabolic process; protein polyubiquitination; ubiquitin-dependent endocytosis; viral budding; protein ubiquitination
Cellular component: cytoplasm; membrane
Genetic constraint (gnomAD): Loss-of-function variants: 96 observed, 120.49 expected, observed/expected ratio (o/e) 0.8, 90% interval 0.67 to 0.94. The upper end of that interval is the gene's LOEUF score, 0.94, which puts it in group 4 of 6, group 1 being the genes least tolerant of losing a copy. Missense variants: 804 observed, 939.55 expected, observed/expected ratio (o/e) 0.86, 90% interval 0.81 to 0.91. Synonymous variants: 322 observed, 374.89 expected, observed/expected ratio (o/e) 0.86, 90% interval 0.78 to 0.94.
Gene-disease validity (ClinGen):
ClinGen rates the evidence that LRSAM1 causes each of these diseases.
Charcot-Marie-Tooth disease axonal type 2P (autosomal dominant): Definitive. Any Charcot-Marie-Tooth disease in which the cause of the disease is a mutation in the LRSAM1 gene.
Homologues: Orthologues: chimpanzee LRSAM1 (99% identical), macaque LRSAM1 (98% identical), dog LRSAM1 (91% identical), rat Lrsam1 (89% identical), mouse Lrsam1 (88% identical), pig LRSAM1 (87% identical), guinea pig LRSAM1 (86% identical), rabbit LRSAM1 (79% identical), tropical clawed frog lrsam1 (61% identical), zebrafish lrsam1 (57% identical).
Diseases named in the same sentence as LRSAM1 in open-access papers:
LRSAM1 is named in the same sentence as 30 diseases in open-access papers, as found by Europe PMC text mining. Sharing a sentence is not in itself a finding about the gene and the disease. The quoted sentences say what the papers report.
Hirschsprung disease (4 papers, 2017 to 2021). Hirschsprung disease (HSCR) is a congenital intestinal motility disorder that is characterized by signs of intestinal obstruction due to the presence of an aganglionic segment of variable extent in the terminal part of the colon. "The neurodevelopmental defect observed in the zebrafish morpholino knock-down of LRSAM1 is reminiscent of the phenotype of individuals suffering from Hirschsprung's disease (HSCR)." (PMID 33568173, 2021). "In terms of the role of miR-431-5p in diseases, down-regulation of this miRNA has been reported to promote cell proliferation by targeting LRSAM1 in Hirschsprung’s disease." (PMID 34234811, 2021).
Charcot-Marie-Tooth disease (3 papers, 2010 to 2020). An inherited degenerative disorder involving the peripheral nerves. "Mutations of LRSAM1 (leucine-rich repeat and sterile alpha motif containing 1), an E3 ligase with RING ZINC finger domains and leucine-rich repeats, are associated with cases of early-onset Parkinson’s disease and to Charcot-Marie-Tooth disease." (PMID 32344852, 2020).
axonal neuropathy (2 papers, 2020 to 2021). Any nerve disorder affecting the axon of a nerve. "Three novel mutations and one novel VUS in LRSAM1 were identified in the London cohort in patients with moderately severe axonal neuropathy and prominent sensory loss." (PMID 31827005, 2020). "CMT2P, associated with dominant and exceptionally recessive LRSAM1 mutations, is usually characterized by slowly progressive axonal neuropathy mainly involving lower limbs, and adulthood onset." (PMID 33568173, 2021).
Charcot-Marie-Tooth disease type 2P (2 papers, 2019 to 2022). "Missense mutation C694R in the RING domain of the LRSAM1 gene results in a dominantly inherited polyneuropathy, Charcot-Marie-Tooth disease type 2P (CMT2P)." (PMID 35842440, 2022). "Leucine Rich Repeat And Sterile Alpha Motif Containing 1 (LRSAM1) has been associated with Charcot-Marie-Tooth disease type 2P (CMT2P)." (PMID 30726272, 2019). "LRSAM1, a RING finger ubiquitin ligase also known as TSG101-associated ligase (TAL), has been associated with Charcot-Marie-Tooth disease type 2P (CMT2P) and to date eight causative mutations have been identified." (PMID 30726272, 2019).
colorectal cancer (2 papers, 2018 to 2019). A primary or metastatic malignant neoplasm that affects the colon or rectum. "Previous studies have shown that LRSAM1 expression levels are significantly increased in colorectal cancer patients, suggesting that abnormal LRSAM1 expression may be involved in cancer progression." (PMID 31592239, 2019). "A recent finding indicates that the level of LRSAM1 is significantly up-regulated in patients with colorectal cancer, implying that the aberrant expression of LRSAM1 may be involved in the cancer progression." (PMID 30380781, 2018).
neuroblastoma (2 papers, 2018 to 2019). Neuroblastoma (NB) is the most common solid, extracranial childhood tumor. "With another approach, double transfection of LRSAM1 siRNA in neuroblastoma SH-SY5Y cells caused a >70% decrease of LRSAM1 levels which also resulted to an approximately 50% reduction of TSG101 levels." (PMID 30726272, 2019). "Recently, we reported that downregulation of LRSAM1 affects the proliferation and morphology of neuroblastoma SH-SY5Y cells, and, overexpression of wild-type LRSAM1 rescues, while the c.2047-1G>A mutant fails to rescue the phenotype of the cells." (PMID 30726272, 2019). "Our findings suggest that depletion of LRSAM1 affects neuroblastoma cells growth and morphology andthat overexpression of the c.2047-1G>A mutant form, unlike the ancestral LRSAM1, fails to rescue the phenotype." (PMID 29845787, 2018).
neuropathies (2 papers, 2014 to 2020). "Our results provide new insights into the pathomechanism of LRSAM1-associated neuropathies, both at the cellular and molecular level." (PMID 24894446, 2014). "The normal CMAP amplitudes, similar to giant MUAPs, may be considered the result of extensive axonal regeneration in LRSAM1-associated neuropathies." (PMID 24894446, 2014). "Our findings suggest that, beyond the typical length-dependent degeneration of motor axons, damage of cell bodies in the anterior horn might play a role in LRSAM1-associated neuropathies." (PMID 24894446, 2014). "Whether loss of TAL expression and functionality contributes to an upregulation of TSG101 in cancer is entirely unclear, and it has not been reported that LRSAM1 mutant mice, which exhibit only a very mild neuropathy phenotype with age, develop any tumors." (PMID 32075127, 2020).
pancreatic cancer (2 papers, 2022 to 2025). "According to the previous study, FYN, LRSAM1, and SEMA6C serve as poor prognostic biomarkers in pancreatic cancer, whereas ERAP2, MET, IL20RB, and CXCL11 indicate improvements." (PMID 36428747, 2022).
renal carcinoma (2 papers, 2020 to 2022). A carcinoma arising from the epithelium of the renal parenchyma or the renal pelvis. "Interestingly, FYN, LRSAM1, IL20RB, CXCL11, S100A1, and MAP3K14 are also well-recognized biomarkers in the prognosis of renal cancer, which is reminiscent of the pancreatic metastasis from renal cell carcinoma in some earlier studies." (PMID 36428747, 2022).
Charcot-Marie-Tooth neuropathies (1 paper, 2014). "This requires the E3 ubiquitin ligase LRSAM1, an AP-3 interactor regulating ESCRT-I sorting activity and whose mutations are linked with Charcot-Marie-Tooth neuropathies." (PMID 25380047, 2014).
glioma (1 paper, 2024). A benign or malignant brain and spinal cord tumor that arises from glial cells (astrocytes, oligodendrocytes, ependymal cells). "LRSAM1 belongs to the RING Finger E3 ubiquitination ligase, which is itself low expressed in gliomas and associated with better patient prognosis." (PMID 39039049, 2024).
Huntington disease (1 paper, 2017). Huntington disease (HD) is a rare neurodegenerative disorder of the central nervous system characterized by unwanted choreatic movements, behavioral and psychiatric disturbances and dementia. "Previous studies showed that mutation of LRSAM1 is associated with neurological disorders such as Charcot-Marie-Tooth and Huntington’s disease." (PMID 29253842, 2017).
liver cancer (1 paper, 2019). An epithelial or non-epithelial malignant neoplasm that arises from the liver. "Our study suggests that LRSAM1 promotes the oncogenic growth of human liver cancer cells." (PMID 31592239, 2019). "By exploring the effects of LRSAM1 on liver cancer cell tumorigenicity, our data may provide a new therapeutic option for HCC patients." (PMID 31592239, 2019).
Salmonella Infections (1 paper, 2025). Infections with bacteria of the genus SALMONELLA. "Comparable results have been obtained in a study analyzing Salmonella infections in HeLa cells where downregulation of LRSAM1 via siRNA increased the intracellular numbers of Salmonella significantly." (PMID 40861495, 2025).
cancer (6 papers, 2018 to 2025). A tumor composed of atypical neoplastic, often pleomorphic cells that invade other tissues. "When receptor ROR2 binds to a small amount of WNT5A, it could slow down the secretion of cytokines and chemokines from cancer cells, regulating the mutated LRSAM1." (PMID 35164166, 2022). "Additionally, genes such as TSC2, FAM134C, USP36, TECPR1, and LRSAM1 are involved in pathways including macroautophagy and selective autophagy, which can contribute to cancer when dysregulated." (PMID 40279344, 2025). "The DDX4 accelerates cell cycle progression by abrogating the G2 checkpoint when overexpressed in cancer cells, while the aberrant expression of LRSAM1 may be involved in the cancer pathology." (PMID 30380781, 2018). "Influenced by the secreted signal of lipid-modified glycoprotein, the dysregulation of protein LRSAM1 could inhibit downstream protein MYB, indirectly reducing the motility of cancer cells." (PMID 35164166, 2022). "Besides, the roles of seven genes (NR1D2, TANK, LRSAM1, PLXNA1, INHBE, HDGF, and ARAF) in SCLC have not been reported, however those genes have been reported to play a vital role in other type cancer." (PMID 34741430, 2021).
tumor (5 papers, 2019 to 2025). "The results demonstrated that LRSAM1 overexpression moderately enhanced tumor growth, as revealed by the tumor growth curves and xenograft weights." (PMID 31592239, 2019). "More importantly, stable silencing of endogenous LRSAM1 by shRNAs targeting different sequences resulted in dramatic decrease in tumor growth, which was indicated by the tumor growth curves and xenograft weights." (PMID 31592239, 2019). "LRSAM1 overexpression in HepG2 cells enhanced in vivo tumorigenicity, whereas LRSAM1 knockdown in this cell line significantly impaired tumor growth." (PMID 31592239, 2019). "Then, we employed subcutaneous tumor formation in nude mice to explore how LRSAM1 might affect the tumorigenic growth of human HCC cells in vivo." (PMID 31592239, 2019). "Interestingly, LRSAM1 overexpression in HepG2 cells only moderately enhanced in vivo tumorigenicity, whereas LRSAM1 knockdown in this cell line significantly impaired tumor growth." (PMID 31592239, 2019). "In our study, the ferroptosis pathway in GSCs, mediated by REST, LRSAM1, and SLC40A1, was morphologically identified through immunohistochemical staining of orthotopic xenograft tumor specimens." (PMID 39039049, 2024). "In human tumor cell lines, PHF23 (PHD finger protein 23) with a PHD-like zinc finger domain interacted with the E3 ubiquitin ligase LRSAM1 (leucine-rich repeat and sterile α motif-containing 1), which negatively regulates ubiquitin-dependent autophagy." (PMID 36036638, 2022).
peripheral neuropathy (2 papers, 2021 to 2022). A disorder affecting the peripheral nervous system. "The domain is crucial for the ubiquitination function of LRSAM1 and CMT mutations disrupt its function, however it remains unknown how this leads to the peripheral neuropathy." (PMID 33568173, 2021). "However, we observed no peripheral neuropathy in naïve Lrsam1+/C698R and Lrsam1C698R/C698R mice up to 2.5 years of age but did find a mildly impaired nerve function during regeneration after nerve injury." (PMID 35842440, 2022).
bacterial infection (1 paper, 2024). "It has been reported that the E3 ubiquitin ligase LRSAM1 regulates ubiquitin-dependent autophagy responsible for bacterial infection." (PMID 38535468, 2024).
brain diseases (1 paper, 2024). "Previous studies have elucidated the relevance of LRSAM1 to brain diseases and its molecular biological mechanisms." (PMID 39039049, 2024).
genetic disorder (1 paper, 2010). "LRSAM1 is a strong candidate for the causal gene for the genetic disorder in our kindred." (PMID 20865121, 2010).
infection (1 paper, 2025). The state of being infected such as from the introduction of a foreign agent such as serum, vaccine, antigenic substance or organism. "By assessing extracellular LDH release, we observed an elevated cell death 3 h, 5 h, and 7 h post infection in LRSAM1-deficient cells compared to NTC cells." (PMID 40861495, 2025). "We observed an increase in cellular cathepsin B activity in LRSAM1-deficient cells upon infection, which confirmed the higher activity of autophagy in these cells compared to NTC control cells." (PMID 40861495, 2025). "The results demonstrated an increase in IκBα degradation as well as an increased phosphorylation of IκBα during infection in LRSAM1-deficient cells, indicating an elevated activity of the NFκB-pathway with increased secretion of IL-6 upon infection." (PMID 40861495, 2025). "During infection of LRSAM1-deficient cells, a significant increase in IL-6 secretion was observed compared to NTC cells." (PMID 40861495, 2025). "In accordance with these findings, our results revealed an increase in apoptotic and necroptotic cell death during infection, which was more pronounced in LRSAM1-deficient cells." (PMID 40861495, 2025). "In addition, an increase in the ratio of infected LRSAM1-deficient to NTC cells was observed from 1 h to 3 h post infection, indicating reduced clearance of intracellular S. aureus in the LRSAM1-deficient cells." (PMID 40861495, 2025). "Throughout the infection, LRSAM1 KO clones #A9 and #A4 consistently exhibited higher intracellular CFU counts compared to control cells." (PMID 40861495, 2025). "We observed a higher infection rate and larger numbers of intracellular bacteria indicating that LRSAM1 is critical for controlling intracellular S. aureus." (PMID 40861495, 2025). "Infection of both LRSAM1 KO and NTC cells showed a marked increase in viable intracellular bacteria at 0.5 h, 1 h and 2 h, followed by decreased bacterial loads at 3 h and 5 h." (PMID 40861495, 2025). "Furthermore, infection with PFA-fixed bacteria had no impact on the induction of cell death in either LRSAM1-deficient cells or NTCs." (PMID 40861495, 2025). "Additionally, ARIH1 has been observed on Salmonella surfaces prior to LRSAM1 during infection." (PMID 40861495, 2025).
neurodegenerative disease (1 paper, 2021). A disorder of the central nervous system characterized by gradual and progressive loss of neural tissue and neurologic function. "Additionally, recent studies have linked LRSAM1 with other neurodegenerative diseases of peripheral and central nervous systems." (PMID 33568173, 2021). "Several independent observations provide an attractive setting for studying LRSAM1 as a possible modifier of different neurodegenerative diseases." (PMID 33568173, 2021). "Although no large GWAS studies identified LRSAM1 as a potential modifier of neurodegenerative disease, all of these individual observations provide an attractive setting for studying LRSAM1 as a possible modifier of neurodegenerative diseases." (PMID 33568173, 2021).
LRSAM1 also shares sentences with these, for which no sentence is quoted: amyotrophic lateral sclerosis (1 paper); Ataxia (1); breast carcinoma (1); gastric cancer (1); neurological disorders (1); Parkinson disease (1); polyneuropathy (1); renal cell carcinoma (1).